LEP (leptin)
Diseases named in the same sentence as LEP in open-access papers (continued):
Sharing a sentence is not in itself a finding about the gene and the disease.
Obesity (continued). "Yet, the mechanism(s) by which the risk of D2R deficiency to obesity phenotypes is reversed by exercise training, especially in the prospective of an interaction between leptin and dopamine signaling pathways in the hypothalamus, should be investigated in a future study." (PMID 30343561, 2018). "In the future, it will be important to determine whether hyperleptinemia associated with obesity further increases osteolysis or whether lowering leptin levels by dietary restriction or pharmacological treatment reduces the osteolytic response." (PMID 30287858, 2018). "Obesity and leptin levels are associated with increased PC risk and development of chemoresistance." (PMID 29719602, 2018). "Our previous study suggests that the leptin/adiponectin ratio may be a reliable parameter to assess the risk of obesity-related disorders in prepubertal children with simple obesity carrying different genotypes of the—11377C>G polymorphism in adiponectin gene." (PMID 30200554, 2018). "Studies indicate that independent of body fat, high serum leptin levels may be an indicator of increased leptin resistance, which predisposes children who are at high risk of adult obesity to weigh more and to have more body fat during childhood." (PMID 30386323, 2018). "The higher expression of vaspin and leptin in PAT might be attributed to the association of obesity." (PMID 29483593, 2018). "Leptin is also involved in the pathogenesis of obesity-associated hypoventilation." (PMID 29675134, 2018). "Furthermore, leptin resistance at the adipocyte level due to local reduction of the leptin receptor has been related to metabolic disorders associated with obesity." (PMID 28744221, 2017). "When leptin is deficient, Smo activity falls and Hh signaling is disrupted, leading to changes in gene expression that induce pericyte senescence that, in turn, compromises tissue health and promotes obesity-related organ damage." (PMID 28427343, 2017). "For example, leptin-deficient (ob/ob) and leptin receptor deficient (db/db) mice have been used for studies of obesity and type II diabetes, demonstrating insulin resistance, hyperleptinemia, hyperphagia and extremely high plasma glucose levels at 6–10 weeks old." (PMID 28265495, 2017). "Inborn errors of the leptin/leptin receptor system in humans are rare conditions caused by mutations in either the leptin or the leptin receptor gene that lead to early onset extreme obesity." (PMID 28007844, 2017). "However, despite a lack of data, there is increasing indirect evidence for modulation of cardiac ion channel function by distinct obesity-associated factors including dyslipidemia, leptin, hyperglycemia, and pro-inflammatory cytokines." (PMID 28680407, 2017). "Additional research is necessary to determine whether or not the pericyte abnormalities that result from mutations in the leptin or ObRb genes also occur during diet-induced obesity." (PMID 28427343, 2017). "Leptin, a hormone produced mainly by adipose tissue, is recognized for its role in the central control of appetite but has also been implicated in platelet aggregation and arterial thrombosis, contributing to obesity-associated cardiovascular disease risk." (PMID 28241462, 2017). "We evaluated the hypothesis that loss of leptin silences Hedgehog signaling in pericytes, multipotent leptin-target cells that regulate a variety of responses that are often defective in obesity, including tissue repair and adipocyte differentiation." (PMID 28427343, 2017). "Thus, adolescents having the higher leptin concentrations are exposed to a greater risk of developing overweight and obesity at an early age." (PMID 28953229, 2017). "Further research is needed to determine how the altered intestinal microbiome that occurs during obesity might contribute to inhibition of Smo that occurs in leptin-deficient HSC." (PMID 28427343, 2017).
Obesity (continued). "We measured bioactive and immunoreactive leptin levels by enzyme-linked immunosorbent assays in fasting serum samples of 70 children with severe (BMI SDS >3) non-syndromic obesity with onset <3 years of life from our Leipzig childhood obesity cohort (n = 1204)." (PMID 28542631, 2017). "While mutations in LEP cause monogenic obesity, there have been numerous research in determining whether genetic variations in or near LEP influences susceptibility to polygenic obesity." (PMID 28615046, 2017). "Furthermore, obesity-associated polymorphisms in the leptin or leptin-receptor do only rarely occur in humans." (PMID 28207798, 2017). "We hypothesize that the ratio of bioactive leptin to immunoreactive leptin could serve as a biomarker for impaired leptin bioactivity due to undetected leptin gene mutations causing monogenic obesity." (PMID 28542631, 2017). "Here we evaluate the hypothesis that leptin deficiency inhibits Hedgehog signaling in pericytes to trigger a pericytopathy that promotes both adiposity and obesity-related organ damage." (PMID 28427343, 2017). "It has been proposed that leptin (strongly reduced in our mice with increasing CR levels) plays an important role as a cell fate modulator via Hedgehog signaling in liver fibrosis and obesity-associated cancer metastasis." (PMID 28768896, 2017). "Besides HPA axis dysfunction and leptin resistance, adipocyte dysfunction is also suggested as an underlying mechanism of obesity-associated inflammation." (PMID 29093685, 2017). "Associations between LEP promoter methylation and obesity in females may be difficult to discern because of the influence of sex hormones on DNA methyltransferases, the enzymes responsible for DNA methylation." (PMID 28360946, 2017). "Thus, hypothalamic inflammation impairs the effects of insulin and leptin, contributing not only to hyperphagia and obesity development but also to the associated dysregulation of glucose homeostasis." (PMID 28592656, 2017). "Additionally, epidemiological evidence suggests that CS correlates with a lower umbilical leptin concentration and a reduced rate of early breastfeeding, both of which were reported to be associated with an increased risk of later obesity." (PMID 29261122, 2017). "The increased risk of T2DM in obesity can partly be described by altered function of adipose tissue, which is a major endocrine organ that secretes a number of active adipocytokines such as leptin, resistin, and adiponectin." (PMID 29062839, 2017). "In addition, leptin has been correlated with several obesity-associated diseases such as cardiovascular diseases and diabetes." (PMID 28076613, 2017). "Obesity is associated with elevated leptin and resistance toleptin effects on energy homeostasis." (PMID 28076453, 2017). "Ob, the first obesity gene to be identified, encodes the fat cell-derived adipokine hormone leptin." (PMID 28427343, 2017). "In addition, Interleukin 1 (IL-1), IL-6 and leptin are also increased in obesity and have been associated with insulin resistance." (PMID 29209160, 2017). "Whereas adiponectin deficiency might be critically involved in the pro-inflammatory state associated with obesity and related disorders, overproduction of leptin, a rather pro-inflammatory mediator, is considered of equal relevance." (PMID 28758929, 2017). "The association of leptin plasma levels with obesity is well known." (PMID 28542631, 2017). "The fact that leptin-deficient HSC are prone to senescence also has potentially important clinical implications as senescent HSC have been implicated in the pathogenesis of obesity-related hepatocellular carcinoma." (PMID 28427343, 2017). "In addition, a variety of single nucleotide polymorphisms (SNPs) in different loci have been associated with circulating leptin levels and obesity." (PMID 28771179, 2017).
Obesity (continued). "While mid-life obesity and systemic metabolic changes, such as high leptin circulating levels, are risk factors in the development of dementia, low plasma leptin levels later in life are associated with worsening cognitive decline and increased risk of developing AD." (PMID 29156608, 2017). "However, in atopic asthmatic children and adolescents, obesity has been associated with increased serum leptin and tumor necrosis factor alpha (TNF-α) levels that enhance eosinophil chemotaxis and adhesion." (PMID 28696379, 2017). "Hence, a biomarker measurable by rather simple means of immunoassay would be beneficial compared to genetic analyses as there appears to be a benefit for the mutation carriers with monogenic obesity from the leptin replacement." (PMID 28542631, 2017). "Very recently, two children with early onset massive obesity due to biallelic missense mutations of the leptin gene leading to formation of leptin with impaired functional activity but preserved immunoreactivity and hence normal leptin levels have been identified." (PMID 28542631, 2017). "Because of this, we hypothesized that the motivational deficit seen in BACHD rats during satiety and the standard food restriction was caused by an obesity-related increase in serum leptin levels." (PMID 28273120, 2017). "Monogenic leptin deficiency results in severe early onset obesity with hyperphagia." (PMID 28542631, 2017). "Besides its beneficial role in reducing obesity risk, leptin is a multifunctional hormone that influences many brain functions including appetite, motivation, learning, memory, and cognition." (PMID 29295472, 2017). "It has been suggested that these obesity's effects could be linked to leptin signaling, which is the main adipokine secreted by adipocytes, and is also synthesized by cancer cells." (PMID 27999190, 2017). "Also, given that both ageing and obesity are risk factors for frailty, an association between higher leptin and increased risk of frailty was to be expected." (PMID 28400989, 2017). "The same association was observed between maternal obesity and cord leptin levels in girls." (PMID 28750045, 2017). "The discovery that the mouse obesity phenotype ob has been attributed to mutations in the mouse leptin gene, and that mutations in the human homolog (LEP) cause early-onset monogenic obesity in humans, has led to significant progress in understanding the etiology of obesity." (PMID 28615046, 2017). "Similarly, in the obese state, leptin sensitivity is retained in the DMH and increased leptin action on these neurons contributes to obesity-associated hypertension presumably via an increase in sympathetic outflow." (PMID 28592656, 2017). "A study by Stone et al27 showed a positive correlation between obesity and pain; explanations for this association include the effects of leptin and other hormones associated with excess fat and physiologic and psychologic factors associated with obesity, among others." (PMID 28717765, 2017). "Hence, the diagnosis in first patients described with bio-inactive leptin as the cause of extreme obesity had to be established by complex molecular genetic investigations." (PMID 28007844, 2017). "In obese individuals, low ZAG gene expression may play an important role in the development of obesity, which is associated with low serum adiponectin and high plasma leptin levels." (PMID 28165362, 2017). "The molecular mechanisms responsible for the increased risk of invasive/metastatic disease with obesity are complex, but may include elevated levels of adipokines such as leptin." (PMID 28542577, 2017). "Leptin G2548A polymorphism, located in the promoter region of the leptin gene, has been demonstrated to correlate with variations in serum leptin levels, degree of obesity, as well as cancer susceptibility." (PMID 28938640, 2017). "Strong evidence implicates PTP1B in obesity-associated hypothalamic leptin resistance." (PMID 28197094, 2017).
Obesity (continued). "All of these observations point to an important role for leptin in asthma-associated obesity." (PMID 28696379, 2017). "SOCS3 has also been linked to the development of leptin resistance during obesity." (PMID 29025435, 2017). "Leptin is associated with obesity and is used as a surrogate marker of energy level." (PMID 28718808, 2017). "Additionally, there are reports regarding association between global methylation levels of Alu–elements and BMI, and association between obesity and DNA methylation levels in leptin (LEP) and adiponectin (ADIPOQ) genes." (PMID 28289477, 2017). "It has been suggested that the extended elevation of GH can disrupt the normal physiological response to hyperleptinemia, thus predisposing towards leptin resistance and obesity, with the most likely mechanism underpinning leptin signaling impairment being at the level of the ARC." (PMID 28786951, 2017). "Leptin-deficient ob/ob mice exhibit massive obesity, dyslipidemia and insulin resistance." (PMID 28584304, 2017). "Moreover, PTP1B and SOCS3 contribute to the development of leptin resistance: Their expression in the hypothalamus is increased by diet-induced obesity, and their deficiency protects mice from the development of leptin resistance." (PMID 28912580, 2017). "In 1999 came what appeared to be the proof of this hypothesis: the reported dramatic reversal of obesity in congenital leptin-deficient children that were treated daily with recombinant leptin." (PMID 28013339, 2017). "Obesity associated to HFD intake is reported to induce central leptin resistance." (PMID 28377744, 2017). "The associations between BMI-increasing loci and increasing leptin levels may partly explain the definitive identification of the specific mechanisms about these loci influence BMI and obesity." (PMID 29212175, 2017). "However, high-fat-diet-induced obesity is not only associated with a central resistance to insulin and leptin." (PMID 28592656, 2017). "Obesity and T2D are associated with increased leptin levels and resistance to leptin action." (PMID 28369078, 2017). "In the present study, we hypothesized that maternal and/or postnatal chocolate and soft drink supplement (S) will affect hypothalamic leptin signalling and astrocyte morphology, predisposing to offspring to obesity." (PMID 28092346, 2017). "In individuals with obesity, leptin levels are associated with leptin resistance." (PMID 28894445, 2017). "Leptin and ghrelin dysregulation has been implicated in both memory and obesity, which may account for observed differences in NW versus OB individuals." (PMID 29291133, 2017). "The aim of this study was to determine whether cord blood leptin and adiponectin werepositively associated with later obesity, BMI, waist circumference, and fat mass andwhether this is independent of maternal BMI." (PMID 27841944, 2017). "In adult rodents with sustained elevated leptin associated with obesity, a profound desensitization to leptin is noted, thus a similar scenario may be occurring in these hypoxic offspring." (PMID 28957383, 2017). "Our hypothesis is that patients with IIHS are more susceptible to OSA due to obesity and/or leptin resistance." (PMID 28929972, 2017). "We here pursued the hypothesis that deleterious post-translational modifications of leptin signalling components occur in response to diets and predispose to obesity." (PMID 26923837, 2016). "Moreover, numerous factors mediating the pathophysiology of leptin resistance, a hallmark of obesity, such as endoplasmic reticulum stress, protein tyrosine phosphatase 1B, and suppressor of cytokine signaling 3 also contribute to insulin resistance." (PMID 27812350, 2016). "The leptin deficient ob/ob mouse is a widely used model for studies on initial aspects of metabolic disturbances leading to type 2 diabetes, including insulin resistance and obesity." (PMID 27713548, 2016). "Loss of leptin function results in several metabolic phenotypes, including obesity in mammals." (PMID 26928023, 2016).
Obesity (continued). "In our previous work, using the same model of diet-induced obesity, we reported a strong relationship between plasma leptin levels and the nutritional status-associated traits, such as the food intake, adiposity or plasma triglycerides and glucose levels in LEW rats." (PMID 27483348, 2016). "The aim of this study was to determine the impact of a perinatal high fat diet on energy metabolism and on leptin as well as insulin sensitivity, early in life and at adulthood in two strains of rats presenting different susceptibilities to diet-induced obesity." (PMID 27618559, 2016). "Scd1, for example, catalyzes the rate-limiting reaction of monounsaturated fatty acid synthesis and is regulated by leptin, a key regulator of obesity-linked diabetes, through insulin independent mechanisms while FASN deregulation is linked to metabolic diseases and insulin-resistance." (PMID 27855634, 2016). "Among the possible mechanisms involved in the pathogenesis of OHS, some studies have reported damage to respiratory mechanics caused by obesity, leptin resistance leading to central hypoventilation, respiratory sleep disorders, and impaired compensatory responses to acute hypercapnia." (PMID 27408717, 2016). "A comparison of bacterial composition in the gut of lean, wild-type, and obese mice (leptin-deficient ob/ob mice, in which obesity is induced by a deficiency in leptin, the hormone that controls satiety) showed differences in the abundance of the phyla Bacteroidetes and Firmicutes." (PMID 27098727, 2016). "In addition, overnutrition by decrease in litter size on postnatal day 1 can lead to increased obesity susceptibility and insulin and leptin resistance after consumption of a HFD in later life." (PMID 27479001, 2016). "Importantly, maternal high fat feeding also rapidly induced leptin resistance in the arcuate nucleus and increased the susceptibility to develop diet-induced obesity in response to a high fat diet during adulthood." (PMID 27618559, 2016). "Additionally, FADD‐D mutation prevents obesity in ob/ob mice and completely corrects the hypometabolic phenotype of leptin deficiency." (PMID 27357657, 2016). "Leptin resistance is considered to be the primary cause of obesity." (PMID 26849804, 2016). "Leptin concentration is elevated in obesity and positively associated with total body fat." (PMID 28050279, 2016). "Furthermore, common human obesity is frequently associated with leptin resistance characterized by an inability of leptin to decrease body weight." (PMID 27609221, 2016). "The leptin-ObR-IL-8 axis may be also one of the mechanisms underlying obesity-induced breast cancer progression." (PMID 27588409, 2016). "In recent years, leptin has been studied as a key factor involved in programming of obesity risk." (PMID 26769798, 2016). "However, there is limited information on specific plasma FA associations with adiponectin, leptin, and C-peptide after adjusting (i.e. statistically) for obesity." (PMID 27023786, 2016). "Furthermore, experiments in high-fat diet-induced obesity, associated with hyperleptineamia (dysfunctional leptin), would be of value to confirm our findings." (PMID 27486384, 2016). "The diet-induced obesity in our wild-type mice, with mean body weights 20% above chow-fed controls, was not accompanied by changes in fasting glucose or insulin levels, but changes were seen in circulating cytokines associated with obesity: leptin, resistin and MCP-1." (PMID 27448965, 2016). "Obesity, as defined by body mass index (BMI) >30 kg/m2 is associated with increased cancer risk, and leptin may be a potential mediator of this association." (PMID 27636369, 2016). "However, mice with haploinsufficiency of SOCS3 showed enhanced leptin sensitivity and were protected against the development of diet-induced obesity and associated metabolic complications." (PMID 27542279, 2016).